UHRF1 (ubiquitin like with PHD and ring finger domains 1)
Diseases named in the same sentence as UHRF1 in open-access papers (continued):
Sharing a sentence is not in itself a finding about the gene and the disease.
tumor (continued). "For instance, in tumor cells, the expression of UHRF1 may be easily noted, while in some terminal differentiation cells, e.g., UHRF1 is hardly expressed in skeletal muscle cells." (PMID 31428652, 2019). "The reactivation of multiple tumor-related genes by combined UHRF1 depletion and HDAC inhibition indicated that this combination may exert a strong antitumor effect." (PMID 31064417, 2019). "Finally, through in vivo ectopic tumor formation experiments, we further confirmed that miR-506 targets UHRF1 to inhibit the proliferation and invasion of CRC by the KISS1/PI3K/NF-κB signaling pathway." (PMID 31803739, 2019). "The function and mechanism of UHRF1 in tumor cell migration, invasion and carcinogenesis remain largely unknown." (PMID 30352833, 2018). "UHRF1 overexpression relates to metastasis, tumor stage, E2F1 levels and poor survival rate." (PMID 28881702, 2017). "However, it is now clearly demonstrated through a recent series of studies that UHRF1 is a tumor promoter." (PMID 28881702, 2017). "Interestingly, UHRF1 has been shown to bind to the methylated promoter region of the p14ARF tumor suppressor, which we also found was significantly downregulated in SENP8-deficient cells." (PMID 28475037, 2017). "UHRF1 overexpression relates to tumor stages, poor prognosis and resistance to radiotherapy." (PMID 28881702, 2017). "UHRF1 overexpression relates to tumor stages, metastasis and low survival rate." (PMID 28881702, 2017). "UHRF1 overexpression relates to tumor stages and lymph node metastasis." (PMID 28881702, 2017). "Furthermore, UHRF1 downregulation can induce G2/M cell cycle arrest and inhibit cell proliferation, tumor aggressiveness, and EMT progression." (PMID 28060737, 2017). "UHRF1 overexpression relates to tumor stages, low survival rate and resistance to radiotherapy." (PMID 28881702, 2017). "Altogether, these results may suggest that elevated UHRF1 expression indicates poor prognosis and promotes tumor progression in HCC." (PMID 28060737, 2017). "UHRF1 overexpression relates to high Gleason score, tumor stages, recurrence and low survival rate." (PMID 28881702, 2017). "UHRF1 overexpression relates to tumor stages, metastasis and poor prognosis." (PMID 28881702, 2017). "Of note, the levels of UHRF1 correlated with distant metastasis, tumor area and HBV." (PMID 28881702, 2017). "The results showed that tumor volumes and weights in the sh-UHRF1 group were obviously lower than those in the sh-NC group, and the tumor growth curves showed that UHRF1 silencing significantly inhibited tumor growth (P < 0.05)." (PMID 28060737, 2017). "Additionally, the proliferative and invasive abilities of tumor cells were significantly inhibited after UHRF1 knockdown, while opposite results were obtained when UHRF1 was upregulated." (PMID 28060737, 2017). "Based on our observed inverse relationship between UHRF1 and Keap1 levels in cell lines, we sought to determine whether this was relevant in patient tumour samples." (PMID 26497117, 2016). "UHRF1 mRNA was overexpressed in NSCLC tumor tissues in comparison to their normal adjacent tissue." (PMID 27437769, 2016). "Moreover, cells depleted of either UHRF1 or Nrf2 showed similar cell cycle profiles, supporting the concept that UHRF1 promotes tumour growth through up‐regulation of Nrf2." (PMID 26497117, 2016). "The presence of UHRF1 is associated with larger tumour size, although a link between UHRF1 expression and outcome was not established." (PMID 26497117, 2016). "If our hypothesis of the tumor cell of origin not being present in the Pax6 TKO retinae, this results suggested that upregulation of Uhrf1 and Hells is only tumorigenic in the context of the tumor cell of origin." (PMID 25338120, 2014). "Six genes, RPL13A, KLF6, LOC100129599, GBE1, PDGFA, and UHRF1 were altered in lymph node metastases of both cell lines relative the primary tumor, suggesting they may represent changes important for metastatic growth in lymph nodes." (PMID 23118918, 2012).
tumor (continued). "The UHRF1 ability to keep promoters in a hypermethylated state, together with the possibility of mediating de novo methylation, gives this factor an important role in cancer development through silencing tumor suppressor genes." (PMID 22848209, 2012). "Interestingly, a strong immunostaining for UHRF1 was observed in the tumours from the control group, whereas low staining was found in those from RWPs-treated group." (PMID 21496237, 2011). "Moreover, the abnormal expression of UHRF1 and SFRP5 is associated with tumor recurrence." (PMID 40301374, 2025). "In addition to PD-1/PD-L1 expression and tumor mutational burden (TMB), several methylation regulators, such as ubiquitin-like with plant homeodomain (PHD) and ring finger domains 1 (UHRF1) and Ten-eleven translocation 1 (TET1), have been reported to be potential biomarkers for ICIs therapy." (PMID 38736884, 2024). "Thus, we hypothesize that therapeutic targeting UHRF1 could lead to reactivation of these TSGs and effectively restrain tumor development." (PMID 37407562, 2023). "The fact that depleting UHRF1 or DNMT1 enhances differentiation of THP-1 cells and inhibiting tumor growth in xenograft mice strongly suggest that targeting UHRF1 or DNMT1 might be a novel therapeutic strategy to treat MLL-AF9 AML by inhibiting cellular proliferation and inducing differentiation." (PMID 37573395, 2023). "We divided tumor cases into high expression group and low expression group by the median expression level of UHRF1 in tumor tissue samples and used tumor data in TCGA to study the correlation between UHRF1 expression and prognosis of patients with different tumors." (PMID 35656341, 2022). "Interestingly, increased UHRF1 epigenetically suppresses tumor KLF6 expression." (PMID 35664070, 2022). "We wondered whether and how tumor UHRF1 impacted TAMs in HCC." (PMID 35664070, 2022). "UHRF1 may inhibit tumor suppressor genes to promote tumor progression." (PMID 35664070, 2022). "Furthermore, we could not exclude that other possibilities including activation of other components in the apoptosis pathway, activation of other cell death pathway or impaired H3K9me2/3 binding of UHRF1 may also contribute to the tumor suppression phenotype." (PMID 33947834, 2021). "Moreover, UHRF1 expression correlated with the tumor stages of patients with NSCLC." (PMID 33658396, 2021). "However, it is also noteworthy that the role of UHRF1 in DNA methylation may differ among tumor types." (PMID 31064417, 2019). "Furthermore, we determined whether UHRF1 suppression could inhibit tumor growth in a xenograft mouse model." (PMID 30174788, 2018). "So, UHRF1 may be a potential biomarker for tumor diagnosis and prognosis." (PMID 30352833, 2018). "Therefore, UHRF1 was essential in cytokine-related tumor inflammatory reaction." (PMID 30174788, 2018). "We concluded that UHRF1 may prompt tumor proliferation in HCC." (PMID 28060737, 2017). "However, whether the overexpressed UHRF1 contributes to the establishment and maintenance of tumor methylomes and whether this process can affect the tumorigenesis remain unclear." (PMID 28467809, 2017). "Instead, a combination of both the depletion of UHRF1 and the inhibition of HDAC has shown promising results in restoring the expression of silenced tumor suppressor genes." (PMID 39051184, 2024). "One study showed that the disruption of either the PHD or SRA domain of UHRF1 impairs its oncogenic properties in CRC, including cell proliferation, anchorage-dependent growth, and tumor metastatic capacity." (PMID 39051184, 2024).
tumor (continued). "UHRF1 coordinates with DNMT1 to ensure DNA methylation during cell division, a key process for silencing tumor suppressor genes and promoting oncogenesis." (PMID 39684755, 2024). "The inhibition of BRPF1 and UHRF1, both containing PHD, overexpressed in liver CSCs, reduces CSC proliferation and survival, curbing tumor growth." (PMID 38813086, 2024). "Meanwhile, SIRT4, as a downstream target of the epigenetic regulator UHRF1, antagonizes the HIF-1α-mediated transcription of glycolytic genes, thereby inhibiting glycolysis, tumor proliferation, and metastasis." (PMID 39682281, 2024). "UHRF1/DNMT1-mediated DNA methylation plays a crucial role in promoting the epigenetic silencing of TSGs and facilitating tumor progression." (PMID 39267107, 2024). "UHRF1 contributes to inhibition of GLI1/Hedgehog and Wnt signaling, resulting in decreased tumor growth and a shift in the expression profile of CSC-specific genes." (PMID 38813086, 2024). "The expression levels of three writers (DNMT1, DNMT3A, DNMT3B), two erasers (TET1, TET3), and eight readers (MBD4, ZBTB33, UHRF1, UHRF2, UNG, TDG, NTHL1, SMUG1) were dramatically higher in tumor tissues (p < 0.05)." (PMID 38317133, 2024). "Similar to UHRF1, high expression of GLI1 in cancerous tissues was also related to advanced tumor stage, poor histological differentiation, and adverse prognosis." (PMID 37380646, 2023). "Indeed, in these mice we could not detect any tumors with complete loss of UHRF1, suggesting that UHRF1 expression is important for tumor development." (PMID 37407562, 2023). "We found that WDR79 depletion increased SIRT4 expression by suppressing UHRF1 expression, and inhibition of SIRT4 expression reversed the anti-tumor effect of WDR79 in PC." (PMID 36712589, 2023). "Blunting UHRF1 activity rebalanced the liver CSC transcriptome toward differentiation and tumor suppression by affecting the transcript levels of master transcription factors." (PMID 37380646, 2023). "knockdown of UHRF1 decreased the recruitment of DNMT1 to the CPG islands, thereby decreasing the maintenace of DNA methylation and re-elevating the epigenetic-silenced tumor suppressor genes such as RARB, CDH1, and PSP94." (PMID 36593255, 2023). "To explore how tumor UHRF1 regulated TAMs, we cultured human HCC TAMs with the supernatants from UHRF1-overexpressing HepG2 cells." (PMID 35664070, 2022). "In consequence, upregulated UHRF1 methylates H3K9 to diminish tumor KLF6 expression, a tumor inhibitory transcriptional factor that directly transcribes miR-520d." (PMID 35664070, 2022). "Inhibition of UHRF1 expression can induce G0/G1 phase arrest or G2/M phase arrest of the CRC cell cycle, thus affecting the proliferation of tumor cells." (PMID 35211429, 2022). "To investigate the mechanisms by which TAM-derived PGE2 stimulates tumor UHRF1 expression, we constructed UHRF1 3'UTR into a luciferase reporter plasmid and cloned the UHRF1 promoter." (PMID 35664070, 2022).
tumor (continued). "Further investigation illustrated that DNMT1/3A/3B, TDG, SMUG1, UNG, NEIL1, MDB3/4, ZBTB33, and UHRF1/2 were essentially upregulated in tumor samples, while TET2, MBD1, and MBD2 were downregulated in tumor samples." (PMID 35205097, 2022). "Again, overexpression of UHRF1 and KLF6, respectively, increased and decreased tumor colony formation and sphere formation." (PMID 35664070, 2022). "To elucidate the mechanism by which TAM-derived PGE2 controls UHRF1 expression, we have demonstrated that PGE2 promoted the dissociation of KLF6, a transcription factor and a tumor suppressor, from the miR-520d promoter, thereby decreasing miR-520d level." (PMID 35664070, 2022). "ANKRD13B, ISG15, KBTBD12, KLHL35, and UHRF1 were upregulated in tumor samples; DCUN1D5, HCK, and SOCS3 were downregulated in tumor than in normal samples." (PMID 35884544, 2022). "In both tumor tissues and plasma exosomal RNA of patients with hepatocarcinoma (HCC), the expression of the UHRF1-derived circular RNA, named circUHRF1, circUHRF1 is increased and is associated with decreased NK cell proportion and tumor infiltration." (PMID 34685721, 2021). "DNMT1 forms complexes with UHRF1 and HDAC1 proteins in tumor cells, reducing expression of tumor suppressor promoter genes (e.g., P16INK4A, P14ARF, and P21) and hence fostering tumor growth." (PMID 33941774, 2021). "The mRNA and protein expression levels of UHRF1, EZH2, TTF2, WHSC1 and RAD54L significantly correlated with tumor stage in NSCLC patients." (PMID 33658396, 2021). "In fact, a previous study reported that UHRF1 forms a complex with HDAC1 and binds to methylated promoters of tumor suppressor genes such as CDKN2A, suggesting that UHRF1 mediates the tumor suppressor repression in cooperation with HDAC1." (PMID 31782885, 2020). "At the molecular level, UHRF1 acts as a transcriptional repressor since it binds to and recruits HDAC1 to the methylated CpG sites near the promoters of tumor suppressor genes." (PMID 31245293, 2019). "In conclusion, our results suggest a disparate role of RP11-424C20.2/UHRF1 axis in the progression of LIHC and THYM by regulating tumor immune escape which is mediated at least partly through IFN-γ-mediated CLTA-4 and PD-L1 pathway." (PMID 31442209, 2019). "Because PDTC reduced in vivo tumor growth in nude mice, we examined the expression of ZNF479, MT-1, ASH2L, Menin, DNMT1, and UHRF1 in PDTC-treated tumors from mice." (PMID 31138789, 2019). "The sizes of tumor xenografts containing UHRF1-depleted DU145-DR cells and treated with docetaxel were much smaller than those containing UHRF1-depleted DU145-DR cells or treated with docetaxel alone." (PMID 29752436, 2018). "Our results revealed that cytokines in ATC cell lines and tumor tissues, including IL-8, TGF-α and TNF-α, were down-regulated by suppression of UHRF1." (PMID 30174788, 2018). "Thus, UHRF1 may act as an oncogene by promoting tumor growth in HCC." (PMID 28060737, 2017). "UHRF1 also recruited SUV39H1 (H3K9 methyltransferase) and DNMTs to the promoter region of many tumor suppressor genes (CDH1, PSP94, RARB) resulting in increased methylation of histones and DNA with subsequent silencing of TSGs." (PMID 28881702, 2017). "We found that the expression of both UHRF1 mRNA and protein in HCC tumor tissues was significantly higher than that in the matched noncancerous tissues." (PMID 28060737, 2017). "In addition, the regulation of UHRF1 by microRNAs could modulate tumor aggressiveness." (PMID 28060737, 2017). "It is also reported that targeting UHRF1 and DNMT1 can affect the global methylation and re-expression of tumor suppressor genes." (PMID 29268763, 2017). "Previous report indicated that UHRF1 and EZH2 synergistically and independently silence tumor suppressors by methylation: UHRF1 induce methylation of tumor suppressor gene DNA CpGs and H3-K9me3, and EZH2 induce methylation of H3-K27." (PMID 27487138, 2016).
tumor (continued). "Uhrf1, which has been reported to be over-expressed in HCC, can recruit the maintenance DNA methyltransferase Dnmt1 to repress tumor suppressor gene expression." (PMID 25549359, 2014). "On the other hand, while lenti-UHRF1 infected tumors grew at the same rate as lenti-GFP, their final tumor size was significantly smaller than the control mice." (PMID 25338120, 2014). "UHRF1 is an oncogene protein known to bind to methylated DNA and to recruit the DNMT1 to regulate tumor suppressor gene expression including p16INK4A." (PMID 23688286, 2013). "UHRF1 and PBK had increased expression in all tumour samples relatively to normal tissue samples, but the highest expression levels were detected in PDTC." (PMID 19809427, 2009). "Notably, several members of the panel, PLK1, UHRF1, and HJURP, have known roles in mitotic regulation and chromatin remodelling, both of which intersect with ferroptotic sensitivity and tumour aggressiveness." (PMID 41007424, 2025). "Mechanistically, UHRF1 binds to YAP1 (the major downstream effector protein of the Hippo signaling pathway) and inhibits the ubiquitination-dependent protein degradation, thereby stabilizing YAP1 protein in tumor cells of SCLC." (PMID 38725075, 2024). "We also found that putative tumor suppressors, such as FOXP1, STK4, and ATM were frequently hypermethylated and silenced whereas oncogenes, such as UHRF1, MPZL1, CDK14, RACGAP1, and RAB13, were hypomethylated and overexpressed suggesting that DNA methylation changes contribute to PTCL development." (PMID 38464090, 2024). "In triple-negative breast cancer (TNBC), a subtype notorious for its poor prognosis and lack of targeted therapies, UHRF1 overexpression reduced the G1 cell population and enhanced tumor growth." (PMID 39051184, 2024). "UHRF1 degradation decreases the recruitment of DNMT1 to chromatin, and decreases the level of genome-wide DNA methylation, thereby elevating the expression of tumor suppressor genes and decreasing cell viability." (PMID 37788997, 2023). "The protein levels of UHRF1, GLI1, CD133, and CD44 displayed similar expression patterns in HCC tumor and paired nontumor tissues, and overexpression (defined as a twofold increase in tumor) of these proteins was observed in nearly 50% of the samples." (PMID 37380646, 2023). "As detected by qPCR and WB, UHRF1 was significantly increased in tumor samples compared to nontumor samples." (PMID 37380646, 2023). "It is also known that several chromatin regulators are misregulated in RB and play a relevant role in tumor transformation following RB1 inactivation, including DNA methyltransferase (DNMT), Ubiquitin-like with PHD and ring finger domains 1 (UHRF1), and B lymphoma Mo-MLV insertion region 1 (BMI1)." (PMID 35432447, 2022). "UHRF1 KO tumors exhibited reduced number of tumor vessels without reducing the overall tumor vessel caliber compared to VC." (PMID 36068209, 2022). "When human HCC TAMs were pretreated with celecoxib, a COX-2 specific inhibitor, which blocked PGE2 production, TAMs failed to stimulate tumor cell UHRF1 expression." (PMID 35664070, 2022). "Simultaneous knockdown of tumor UHRF1 and macrophage depletion did not have additional effect on tumor progression and mouse survival." (PMID 35664070, 2022). "Taken together, we concluded that SHMT2 could regulate the cell cycle by targeting UHRF1 in CRC cells, which in turn promoted tumor progression, leading to poor prognosis in CRC patients." (PMID 35211429, 2022). "Furthermore, we analyzed the expression levels of UHRF1 and BCL2L11 in the TCGA_CHOL cohort and confirmed that UHRF1 and BCL2L11 were highly expressed in tumor tissues than in the adjacent normal tissues." (PMID 35449153, 2022).